TIMP2 (TIMP metallopeptidase inhibitor 2)
Diseases named in the same sentence as TIMP2 in open-access papers (continued):
Sharing a sentence is not in itself a finding about the gene and the disease.
prostate carcinoma (continued). "RUNX3 overexpression in prostate cancer cells showed inhibition in cell migration and invasion with an upregulation of tissue inhibitor of matrix metalloproteinase-2 (TIMP-2)." (PMID 33298014, 2020). "LncRNA DANCR has many physiological functions, for example, lncRNA DANCR was reported to enhance invasion activity of prostate cancer cells through downregulating the expression of TIMP2/3." (PMID 31931700, 2020). "They found that TIMP2/3, which are critical metastasis inhibitor of prostate cancer, were down-regulated by DANCR synergistically with EZH2 through epigenetically silencing their promoter." (PMID 33123287, 2020). "The latest study validated RBL1, KLF5, SMAD4, and TIMP2 as the direct miR-888 targets in prostate cancer." (PMID 33123477, 2020). "Evidence demonstrated that DANCR enhanced the migration and invasion of prostate cancer cells or gastric cancer cells through impeding TIMP2/3 expression or lncRNA-LET." (PMID 31827393, 2019). "TIMP-2 -418GC genotype showed a protective effect against prostate cancer (32.6% vs. 14.8%, P = 0.037, OR = 0.346)." (PMID 31275061, 2019). "Jia J persisted that DANCR promoted the invasion ability of C4-2B and CW22RV1 cells through epigenetically silencing TIMP2/3 expression in a research of prostate cancer." (PMID 29753317, 2018). "The lncRNA, DANCER represses TIMP2/3 expression by mediating the binding of EZH2 on their promoters thereby promoting prostate cancer invasiveness." (PMID 28410242, 2017). "Mechanistically, we found that TIMP2/3, which are critical metastasis inhibitor of prostate cancer, were down-regulated by DANCR synergistically with EZH2 through epigenetically silencing their promoter by chromatin immunoprecipitation assay." (PMID 27191265, 2016). "Considering the critical role of TIMP2/3 (TIMP metallopepitidase inhibitor 2/3) plays in prostate cancer invasion, we focused on how DANCR represses the expression of these two genes." (PMID 27191265, 2016). "In the current study, we found that restoration of RUNX3 in prostate cancer cells simultaneously up-regulated TIMP-2 expression, which is the negative regulator of MMP-2." (PMID 24475196, 2014). "HSA/TIMP-2 protein was ip injected into the MLL-Luc prostate cancer xenografts every other day for two weeks based on our previous pharmacokinetic results." (PMID 22545131, 2012). "Furthermore, resveratrol inhibited the migration and invasion of prostate cancer cells by promoting demethylation and increasing the expression of tissue inhibitors of metalloproteinases, TIMP2, and TIMP3 and by suppressing the expression of MMP-2 and MMP-9." (PMID 37446252, 2023). "Furthermore, re-expression of TIMP-2 in metastatic prostate cancer cells significantly inhibited cell invasion." (PMID 38276258, 2023). "We now have a better understanding about how apelin-mediated miRNA and TIMP2 synthesis contributes to prostate cancer cell motility, which may help investigators design more effective treatment for metastatic disease." (PMID 36291151, 2022). "Thus, apelin induces TIMP2-dependent prostate cancer motility by increasing miR-106a-5p expression via the c-Src/PI3K/Akt pathway." (PMID 36291151, 2022). "In addition, apelin stimulation increases miR-106a-5p expression, while treatment of prostate cancer cells with the miR-106a-5p inhibitor reversed apelin-induced inhibition of TIMP2 synthesis and promotion of cell migration and invasion." (PMID 36291151, 2022). "Apelin facilitates TIMP2-dependent migration and invasion of prostate cancer cells." (PMID 36291151, 2022). "c-Src, PI3K and Akt inhibitors, as well as their respective siRNAs, inhibited apelin-facilitated promotion of miR-106a-5p synthesis, suggesting that apelin inhibits TIMP2 synthesis and facilitates prostate cancer migration by increasing miR-106a-5p production through the c-Src/PI3K/Akt pathway." (PMID 36291151, 2022).
prostate carcinoma (continued). "Our results also reveal that apelin enhances PI3K and Akt phosphorylation, which was antagonized by the c-Src inhibitor, suggesting that c-Src-dependent PI3K/Akt activation mediates apelin-controlled TIMP2 synthesis and the metastasis of human prostate cancer cells." (PMID 36291151, 2022). "Yet to our knowledge, and following exploration of the TCGA PanCancer Atlas dataset available via cBioportal, an altered expression of AKT1, CAV1, THBS1, or TIMP2 has not been previously associated with progression to aggressive prostate cancer." (PMID 34596356, 2021). "In addition, DANCR was upregulated in human prostate cancer tissues and cell lines and promoted invasion of prostate cancer by repressing expression of TIMP2/3." (PMID 32099526, 2020). "TIMP-2 -418G/C and 303C/T polymorphisms were associated neither with the risk of developing prostate cancer nor with the risk of cervical cancer." (PMID 31275061, 2019). "Moreover, a direct relationship between EZH2 and TIMP2/3-tissue inhibitors of metalloproteinase-results in enhanced proteolytic activity of MMP-9 in prostate cancer cells." (PMID 28410242, 2017). "However, the role of histone methylation in TIMP2 expression regulation was reported only in prostate cancer cells." (PMID 28620234, 2017). "Collectively, our results suggest that AR up-regulates TIMP2/3, suppresses invasion and migration of prostate cancer cells and inhibits the expression of DANCR; moreover, DANCR impedes the upregulation of TIMP2/3 and the suppression of invasion and migration by androgen-AR signaling pathway." (PMID 27191265, 2016). "Thus, apelin facilitates prostate cancer disease by inhibiting TIMP2 expression." (PMID 36291151, 2022). "Moreover, we demonstrated that RUNX3 overexpression inhibited prostate cancer cell migration and invasion resulting from the elevated upregulation of tissue inhibitor of matrix metalloproteinase-2 (TIMP-2), which subsequently inhibited metalloproteinase-2 (MMP-2) expression and activity in vitro." (PMID 24475196, 2014). "Down-regulation of the TIMP2 gene in prostate cancer cells was shown to be associated with promoter methylation, suggesting that epigenetic regulatory factors, such as HDAC and DNMT, may be involved in regulation of TIMP2." (PMID 22272343, 2012). "The addition of SE to in vitro prostate cancer cells reduced MMP-2 and MMP-9 activity and the expression of nuclear transcription factor-kappa B, and increased TIMP-2 activity." (PMID 37623846, 2023). "In prostate cancer, the inhibition of TIMP2 expression enhances ECM degradation, promoting the motility and metastasis of prostate cancer cells." (PMID 36291151, 2022). "Treating prostate cancer cells with PI3K and Akt inhibitors or transfecting them with PI3K and Akt siRNAs reversed apelin-mediated effects upon TIMP2 synthesis, cell motility and miR-106a-5p synthesis." (PMID 36291151, 2022). "In prostate cancer survivors with history of radiation therapy, elevated levels of PAI 1, TIMP1, TIMP2, HGF and VEGF-A were detected in patients that received a radiation cystitis diagnosis." (PMID 33119677, 2020). "In human prostate cancer cells, DANCR binds to EZH2 and inhibits the expression of TIMP-2 by epigenetic silencing." (PMID 29416741, 2018). "Our results indicate that androgen-AR signaling up-regulates TIMP2/3 and DANCR impedes this up-regulation in prostate cancer cells." (PMID 27191265, 2016). "TIMP2 is a main negative regulator of MMP2 enzyme activity and is involved in several tumor metastasis processes, including prostate cancer." (PMID 24475196, 2014). "Western blot was used to examine the TIMP-1, TIMP-2, MMP-2 and MMP-9 expressions in prostate cancer cells." (PMID 24475196, 2014). "We found that high levels of EZH2 expression during cancer progression induce repression of TIMP genes (TIMP2 and TIMP3), leading to increased activity of MMP-9 and thus to increased invasive activity of prostate cancer cells." (PMID 22272343, 2012).
prostate carcinoma (continued). "Here, we show that EZH2 plays an active role in this process by repressing the expression of TIMP2 and TIMP3 in prostate cancer cells." (PMID 22272343, 2012). "To quantify the inhibitory effect of HSA/TIMP-2 on tumor growth with BLI, we used a luminescent cancer xenograft with a rat prostate cancer MLL cell line stably expressing firefly luciferase." (PMID 22545131, 2012). "Patients with prostatic cancer had higher levels of TIMP-1 and collagenase (P = 0.0001) and lower levels of TIMP-2 (P = 0.003) than controls." (PMID 8080738, 1994). "The anti-cancer nature of TIMP-2 is supported by the results of studies in which the downregulation of TIMP-2 was observed, among others, in malignant gliomas or in the progression of prostate cancer." (PMID 32751899, 2020). "In addition, using a prostate cancer model, CXCR4-dependent migration was shown to increase matrix metalloproteinase-9 (MMP-9) expression and decrease TIMP metallopeptidase inhibitor 2 (TIMP2) expression, contributing to a more invasive phenotype." (PMID 27618899, 2016). "On the other hand, DANCR knockdown facilitated the upregulation of TIMP2/3 and the suppression of invasion and migration by androgen-AR, while DANCR knockdown decreased the promotion of invasion and migration in prostate cancer cells by enzalutamide treatment." (PMID 27191265, 2016). "RUNX3 suppresses prostate cancer metastasis due to the imbalance between MMP-2 and TIMP-2." (PMID 24475196, 2014). "However, at lower doses (less than 40 mg/kg), HSA/TIMP-2 demonstrated a stimulative effect on prostate cancer xenografts (data not shown)." (PMID 22545131, 2012).
diabetes (31 papers, 2008 to 2025). "The main limitations of TIMP2*IGFBP7 are decreased diagnostic values in diabetes (possibility of false-positive measurements occurrence) and relatively high cost." (PMID 39596140, 2024). "However, we found an independent association between diabetes and elevated [TIMP-2]·[IGFBP7] levels." (PMID 25866432, 2015). "To date, only one study has examined the effects of quercetin on proteins involved in extracellular matrix degradation, specifically matrix metalloproteinase-2 (MMP-2) and its inhibitor, tissue inhibitor of metalloproteinase-2 (TIMP-2), in a diabetes model." (PMID 39795285, 2024). "Diabetes and OA often co-exist in older adults, and TIMP2 is involved in cartilage destruction in OA." (PMID 35207422, 2022). "In particular, plasma concentrations of TIMP1 and TIMP2 are higher in patients with metabolic syndrome and diabetes, and gene deletion of TIMP-2 in C57Bl/6 mice induces obesity in HFD feeding (60% fat)." (PMID 33803198, 2021). "Analyses of associations with hyperlipidemia, between TIMP-2 and diabetes, as well as the association between MMP-2 isoforms and TIMP-2 with hypertension were also impossible in our control group–also due to the tiny tissue samples." (PMID 30794673, 2019). "MMP-2 mRNA and protein levels were significantly higher in the diabetes group than in negative controls (P < 0.001); meanwhile, gene and protein TIMP-2 expression was also higher in diabetes group." (PMID 26526881, 2015). "The roles of certain cytokines and molecules, such as IL-4, TNF-γ, and TIMP-2, in driving the progression of periodontal disease and alveolar bone loss in individuals with diabetes, have not been completely clarified." (PMID 40075856, 2025). "Urine output and the presence of comorbid conditions (CKD, diabetes mellitus, heart failure) may affect the predictive accuracy of TIMP-2." (PMID 39001241, 2024). "Patients with pulmonary disease and diabetes had higher [TIMP-2]·[IGFBP7] levels on admission." (PMID 25866432, 2015). "Diabetes was independently associated with higher [TIMP-2]·[IGFBP7] levels (P = 0.02) but AKI was not (P = 0.24)." (PMID 25866432, 2015). "The study found that CRP, MMP-2, MMP-14, TIMP-2, and IFN-γ contribute to the inflammatory processes driving periodontal damage in diabetes." (PMID 40075856, 2025). "Other research groups reported that co-morbid illnesses such diabetes mellitus, cardiovascular disease, and chronic kidney disease (CKD) can affect TIMP-2 levels." (PMID 39001241, 2024). "In the present study, diabetes upregulated MMP2, TIMP1, and TIMP2 mRNA expression in the human rotator cuff." (PMID 35453426, 2022). "The molecular mechanisms in the pathways regulating TIMP-2 and MMP-2 expressions have been introduced in many diseases, especially diabetes, or different diseases other than diabetes." (PMID 33777140, 2021). "In vivo, the ratio of MMP2/TIMP2 and MMP9/TIMP1 was also elevated in the skin of diabetes mice by qPCR analysis Therefore, MMP-2 and MMP-9 inhibitors were administered to the STZ-induced diabetic mice to evaluate the changes in skin collagen in vivo." (PMID 34777244, 2021). "The imbalance of MMP-2/TIMP-2 and MMP-9/TIMP-1 contributes to the skin disorder of collagen deposition in diabetes patients, providing ideas for managing diabetes skin complications early." (PMID 34777244, 2021). "On the other hand, the genetic deletion of TIMP-2 in mice promotes HFD-induced obesity and diabetes and exercise has been reported to exert a positive effect in TIMP-2 modulation, improving insulin sensitivity." (PMID 31581657, 2019). "To investigate if TIMP concentrations differed in the obtained control and diabetes samples we performed Western blotting with antibodies against TIMP-1 and TIMP-2." (PMID 19758433, 2009).
diabetes (continued). "Patients with comorbidities such as hypertension, obesity, and diabetes had elevated DPPIV, MMP-8, and TIMP-4 levels, and reduced MMP-3 and TIMP-2 levels, indicating a link between these markers and the exacerbating effects of comorbidities on COVID-19 outcomes." (PMID 40557167, 2025). "Decreased serum levels of TIMP-1 and TIMP-2 have been observed in patients with T2D and DN compared to diabetes alone or non-diabetes chronic renal failure." (PMID 37237955, 2023). "After screening the target genes TIMP2 and MAPK1 that efficiently bound to miR-483-5p, we probed into whether TIMP2 and MAPK1 influenced the regulation of miR-483-5p on renal TECs in diabetes under HG conditions." (PMID 33692334, 2021). "While we speculate that alteration of TIMP2 and COL6A3 in human DPN results in ECM remodeling, further investigation will determine how these changes impact nerve function in diabetes." (PMID 32787975, 2020). "In contrast to the Sapphire trial, we found an independent association between urinary [TIMP-2]·[IGFBP7] and diabetes, but not with evolving AKI." (PMID 25866432, 2015). "Some comorbid conditions other than diabetes mellitus such as renal scars, nephrotic syndrome, focal segmental glomerulosclerosis, pancreatic cancer and chronic kidney failure may also affect urine MMP2 and MMP9, TIMP1 and TIMP2 and TGF-β1 concentrations." (PMID 30396876, 2019). "However, large validation studies of the Nephrocheck test showed that urine [IGFBP7]*[TIMP-2] values were not elevated in patients with stable chronic morbidities such as diabetes mellitus, congestive heart failure and CKD who did not have AKI and were not affected by sex or age." (PMID 35207297, 2022). "The imbalance of MMP2/TIMP2 and MMP9/TIMP1 contributes to the non-injured skin disorder of collagen deposition in diabetes, suggesting a possibility for early treatment of diabetes skin complications." (PMID 34777244, 2021). "Further adjustment for height, body mass index, systolic blood pressure, antihypertension therapy, diabetes status, current smoker, current alcohol use, and total and HDL cholesterol did not appreciably change point estimates for MMP-2, TIMP-2, VCAM-1, or SLPI." (PMID 34521347, 2021).
gastric cancer (31 papers, 2006 to 2025). A primary or metastatic malignant neoplasm involving the stomach. "The example came from a gastric cancer study in which the diminished TIMP-2 expression related to the gene promoter polymorphism contributed to rapid dissemination and worse patient survival." (PMID 23108733, 2013). "TIMP-2 303G/A and -418G/C polymorphisms were associated with gastric cancer patient." (PMID 31275061, 2019). "TIMP-2 gene mutation is associated with the occurrence of multiple diseases, including alcohol induced osteonecrosis of the femoral head, emphysema and paraseptal emphysema, and gastric cancer." (PMID 31088428, 2019). "The correlation between the genetic variants of TIMP-2 and susceptibility to stroke, oral squamous cell carcinoma, prostate cancer, abdominal aortic aneurysm, head and neck squamous cell carcinoma, and gastric cancer have been identified in a number of studies worldwide." (PMID 31088428, 2019). "We also found that PITX2 facilitated or repressed the lysosomal exocytosis of many SASP proteins, including MMP2, IGFBP2, and TIMP2, in senescent gastric cancer cells." (PMID 40995693, 2025). "Building on this, a study conducted in 2010 by Shen unveiled that B3GNT8 plays a role in regulating matrix metalloproteinase 2 (MMP-2) and tissue inhibitor of metalloproteinase 2 (TIMP-2) in gastric cancer cells." (PMID 38097951, 2023). "TIMP2 was also demonstrated to interact with multiple integrin pathways and is involved in angiogenesis in gastric cancer." (PMID 33692952, 2021). "In that context, a recent study using bioinformatics has reported TIMP-2 as a poor prognostic indicator in gastric cancer; in addition, TIMP-2 has been shown to regulate matrisome-associated genes in cancer." (PMID 35047406, 2021). "TIMP-2 (-418G/C, 303G/A) polymorphisms and haplotype CGC were associated with the risk of gastric cancer and abdominal aortic aneurysm (AAA)." (PMID 31275061, 2019). "The frequency of haplotype CGC (MMP-2-1306C/T, TIMP-2 -418G/C and 303G/A) was apparently higher in patients with gastric cancer than the control group (P<0.05)." (PMID 31275061, 2019). "Taken together, our results provided evidence that TIMP2 is a direct target of miR-93 and mediates miR-93 promotion of gastric cancer progression." (PMID 29220395, 2017). "In this study, we demonstrated that both mRNA and protein levels of TIMP2 were decreased after up-regulation of miR-93 in gastric cancer cells, but increased via anti-miR-93." (PMID 29220395, 2017). "Transfection of si-TIMP2 significantly decreased the protein level of TIMP2 in gastric cancer cells." (PMID 29220395, 2017). "Taken together, these results suggest that MMP-9, TIMP-2 and cathepsin K at least partially contribute to coronin 3-mediated gastric cancer metastasis." (PMID 22974233, 2012). "Several studies have focused on the prognostic values of CAF-related genes in other cancers, a 4-CAF-gene (COL8A1, SPOCK1, AEBP1 and TIMP2) prognostic signature was developed to predict the clinical outcomes and the response to anti-tumor therapies in gastric cancer." (PMID 35873482, 2022). "However, TIMP2 is a poor prognostic marker in gastric cancer, in contrast to its role in colorectal cancer." (PMID 34781885, 2021). "By using bioinformatics and luciferase reporter assay, it was revealed that TIMP2 was a direct target of miR-93 and could reverse oncogenic functions of miR-93 in gastric cancer." (PMID 29220395, 2017). "Furthermore, silencing of TIMP2 enhanced migration and invasive ability of gastric cancer cells, which was consistent with the result obtained from the up-regulation of miR-93." (PMID 29220395, 2017). "Moreover, the expression of miR-93 was negatively correlated with that of TIMP2 in gastric cancer tissues." (PMID 29220395, 2017).